INS (insulin)
Diseases named in the same sentence as INS in open-access papers (continued):
Sharing a sentence is not in itself a finding about the gene and the disease.
diabetes (continued). "Patients attending public clinics were more likely than private patients to be female, have vascular disease recorded, to be prescribed insulin, make more clinic visits per year, and to have been diagnosed with diabetes for a greater duration." (PMID 21676257, 2011). "The potential role of insulin and/or diabetes in precipitating or accelerating AD has been reviewed extensively (representative examples)." (PMID 22654727, 2011). "Both receptors have been related with obesity, non-Hodgkin's lymphoma, non-insulin-dependent diabetes mellitus, essential hypertension, and resistance to insulin." (PMID 21943151, 2011). "Among the glucose and insulin profiles, the pre-diabetes group had higher levels of fasting glucose, fasting insulin, post load glucose and post load insulin." (PMID 21219665, 2011). "The treatment of diabetes mellitus mainly revolves around oral hypoglycaemic drugs and insulin replacement therapy." (PMID 21747828, 2011). "In the diabetes group 6 (23%) were treated with insulin alone, 9 (35%) with oral antidiabetic drugs alone and two (8%) with both therapies." (PMID 26859486, 2011). "Specifically, low-frequency EA improved insulin sensitivity in a mouse model of genetic insulin resistance and diabetes, at least in part, via stimulation of SIRT1/PGC-1α in the skeletal muscle." (PMID 20981161, 2011). "The incretin effect, described as the enhanced response of insulin release after an oral glucose load, has been shown to be reduced in diabetes mellitus." (PMID 21747829, 2011). "In that pigs are plentiful and have renal function very similar to humans, and because porcine insulin works well in humans, the pig has been suggested as a kidney or pancreas organ donor for humans with chronic kidney disease or diabetes." (PMID 21234246, 2011). "With several established treatment options available for diabetes mellitus including various human insulin preparations and IAs and the expectation of long term use of a new IA, safety aspects are crucial." (PMID 21736748, 2011). "The total insulin content and insulin secretion were significantly lower in sedentary diabetics compared to controls." (PMID 21912535, 2011). "These parameters indicate that the enrolled patients had relatively long duration of diabetes, mild obesity, high frequency of insulin use, and high dosage of insulin." (PMID 22132774, 2011). "After the steroid treatment started, she developed steroid-induced diabetes, and her diabetes has been treated by premixed insulin (insulin lispro mix 50/50, 14 units before breakfast and 6 units before dinner)." (PMID 22393347, 2011). "DEX as an example of GC induces hyperglycemia either in situations of normal glycemia or even in case of diabetes under insulin therapy or oral antidiabetic drugs." (PMID 21910912, 2011). "There is substantial evidence that HNF-4 has a unique role in glucose-dependent insulin secretory pathways, since mutations within the HNF-4α gene are linked to the monogenetic disorder Mature Onset Diabetes of the Young (MODY-1)." (PMID 21731631, 2011). "In the insulin group, 78 (54.2%) reported hypoglycaemia and those with cognitive impairment gave more incorrect responses when asked about diabetes management." (PMID 21166853, 2011). "When considering the potential interactions between diabetes, particularly hyperinsulinemia, and AD, the most convincing evidence has come from a range of studies on insulin degrading enzyme (IDE)." (PMID 22654727, 2011). "Regarding diabetes therapy previous to admission in patients with clinical diabetes, 30% received dietary advice only, 48% took oral antidiabetic agents and 30% used insulin." (PMID 21569580, 2011). "Insulin mimetic, small molecules that possess insulin like activity have the potential to act as therapeutic agents for prevention and management of diabetes." (PMID 22073153, 2011).
diabetes (continued). "In contrast to patients with sporadic disease, who were shown in some cases to manifest insulin resistance or diabetes, our patients displayed increased insulin sensitivity accompanied with elevated serum osteocalcin levels." (PMID 21738662, 2011). "The diabetes susceptibility of the obese BTBR mice has multiple causes, including an insulin secretion defect and a failure to increase β-cell mass." (PMID 21998599, 2011). "We then studied the effects of both treatments on the insulin signaling pathway and its disruption during diabetes." (PMID 22046295, 2011). "Considering the 144 individuals taking insulin, the proportion and frequency of glucose testing was higher than the overall population with diabetes (P < 0.001 for each)." (PMID 21166853, 2011). "The aim of diabetes therapy has always been to mimic the basal and mealtime components of endogenous insulin secretion." (PMID 21978524, 2011). "In order to better understand the relationship, it is important to consider levels of insulin, glucose, and other diabetes related biomarkers such as adiponectin." (PMID 22205924, 2011). "The one drawback in linking diabetes and insulin to AD has been the postmortem studies of diabetic brains demonstrating that AD pathology was not increased; in fact decreased pathology has often been reported." (PMID 22654727, 2011). "The expression patterns of Kcne2, Nppa, and Dcps provide examples of how restoration of insulin and euglycemia can normalize diabetes-induced gene expression alterations that have occurred before initiation of therapy to non-diabetic levels." (PMID 21575160, 2011). "Stepwise intensification of insulin treatment to match the progressive decline of endogenous insulin secretion has been shown to be an effective management strategy in type 2 diabetes mellitus (T2DM)." (PMID 21679291, 2011). "Recent studies in humans and in rodent models of insulin resistance, diabetes and obesity implicate an important role for insulin/IGF-I signaling in β-cell biology." (PMID 22140505, 2011). "Insulin autoantibodies (IAA) are the first to be detected in children at risk for T1D and carry a high positive predictive value for diabetes in siblings of T1D patients." (PMID 21785617, 2011). "Over the past 4 years, diabetes research at Cambridge University has focused on the development and testing of overnight closed-loop insulin delivery systems." (PMID 22071283, 2011). "Over 55% of the patients needed insulin and about 33% of type 2 patients have become insulin requiring during the course of their diabetes." (PMID 22185229, 2011). "Diabetes mellitus is a complex and multifactorial disease indulging severe insulin dysfunction in conjunction with gross abnormalities in glucose homeostasis, lipid and protein metabolism." (PMID 23675214, 2011). "Approximately one third of people with diabetes were managed by diet alone, approximately half were on oral medication, usually on its own, and just over 10% were taking insulin, again as the sole glucose-lowering agent." (PMID 21166853, 2011). "Circumscript, progressing lipoatrophy at the insulin injection sites is an unexplained, however rare condition in diabetes mellitus." (PMID 22145998, 2011). "H3K56 is acetylated by CBP and p300, and deacetylated by SIRT1, all are proteins with important roles in diabetes and insulin signaling." (PMID 21655096, 2011). "Adiponectin levels are positively correlated with insulin sensitivity, and decreased levels of adiponectin are observed in insulin-resistant conditions including type 2 diabetes mellitus." (PMID 21736747, 2011). "Animal models of diabetes demonstrate a similar phenomenon of DR development even with insulin therapy as the longitudinal clinical studies." (PMID 21575160, 2011). "More than half (57%) of diabetes-induced mRNA changes (789 probes) observed at three months were fully normalized to control levels with insulin therapy, while 37% of probes were only partially normalized." (PMID 21575160, 2011).
diabetes (continued). "Subgroup analysis of diabetic subjects on basis of RI values showed that the groups differed significantly only in the treatment received for diabetes with patients with significant proportion of patients with RI < 0.8 on Insulin therapy." (PMID 21748022, 2011). "Duration of T1DM, attendance to diabetes education sessions and seminars, insulin regimen, rate of SMBG, Tanner staging, regularity of physical exercise, and serum HbA1c were reviewed from patient clinical and laboratory records." (PMID 22155463, 2011). "Numerous lines of evidence support the involvement of fatty acids in type 2 diabetes mellitus, and many studies have demonstrated that fatty acids with different degrees of saturation have different effects on insulin sensitivity and glucose/lipid metabolism." (PMID 21774832, 2011). "The current paper examines advances in the field of stem cell therapy for the treatment of diabetes and outlines the varied approaches that have been used to create insulin-producing cells." (PMID 21716654, 2011). "Since the introduction of insulin as a treatment for diabetes, mortality and morbidity rates have improved; still, they remain significantly higher than those of the general population." (PMID 21501437, 2011). "Nitric oxide signaling involved in the regulation of food intake and insulin signaling, is altered in obesity and diabetes." (PMID 21569551, 2011). "The results of present study provides impetus for further molecular and mechanistic studies on the therapeutic action of LH II, before it can be administered as possible insulin replacement or adjuvant in the management of diabetes mellitus." (PMID 21811514, 2011). "To establish the physiological relevance of the in vitro findings, we also studied insulin-resistant Zucker Diabetic Fatty (ZDF) rats." (PMID 22087313, 2011). "SOCS3 and PTP1B levels were not significantly increased in the diabetic subjects, but it is well-established that patients with type 2 diabetes mellitus have defects in the insulin signaling cascade that stimulate GLUT4 translocation." (PMID 22114711, 2011). "A similar trend has been documented in UK Prospective Diabetes Study (UKPDS) 33 in which case a significant proportion of patients on sulfonylurea subsequently required insulin due to severe hyperglycemia." (PMID 22185229, 2011). "Individuals with Laron syndrome who carry mutations in the growth hormone receptor (GHR) gene that lead to severe congenital IGF-1 deficiency with decreased insulin/IGF-1 signaling (IIS) exhibit reduced prevalence rates of acne, diabetes and cancer." (PMID 21699736, 2011). "Systemic insulin treatment allows for relatively good control of diabetes through mechanisms that can be attributed to normalization of the glycemic levels and activation of insulin signaling pathways in various tissues." (PMID 22046295, 2011). "Of note, diabetes requiring treatment with medication (oral hypoglycaemics or insulin) was uncommon, with only four women in the cohort meeting these criteria." (PMID 21843356, 2011). "Type 2 diabetes mellitus, a worldwide health issue, is a cluster of metabolic diseases characterized by hyperglycemia that result from defects in insulin secretion or/and action." (PMID 21774832, 2011). "For many patients with type 2 diabetes, initiation of insulin therapy marks the transition of their diabetes condition into a more severe disease state with the potential for more complications." (PMID 21226935, 2011). "To examine effects of insulin concentration on the association of GLUT1 Enh2 genotypes and albuminuria, we stratified by insulin concentrations excluding those with diabetes (to avoid confounding due to insulin treatment for diabetes)." (PMID 21247498, 2011). "The safety of oral antifungal agents for people with diabetes, especially those taking insulin or oral hypoglycaemic medications has raised much interest." (PMID 22136082, 2011).
diabetes (continued). "When the demand for insulin exceeds the compensatory mechanisms of the body, it leads to chronic hyperglycemia, which is defined as diabetes mellitus." (PMID 22102895, 2011). "Transcriptomic alterations in response to diabetes (1376 probes) were clustered according to insulin responsiveness." (PMID 21575160, 2011). "The UK Prospective Diabetes Study found that intensive treatment with sulfonylurea or insulin reduced micro-vascular complications by 15%." (PMID 23554718, 2011). "Four days after insulin treatment was started, our patient's ulcer had healed and she was discharged from the hospital and follow-up was arranged at her local diabetes clinic." (PMID 22051138, 2011). "Age, gender, race/ethnicity, smoking status, alcohol intake (g/day), level of education, history of diabetes and oral hypoglycemic intake or insulin administration, and antihypertensive medication use were assessed using a questionnaire." (PMID 22114591, 2011). "The adipocytokine adiponectin (ADPN) is downregulated in type 2 diabetes mellitus (T2DM) and coronary artery disease and shows an inverse correlation with insulin sensitivity and cardiovascular disease risk." (PMID 21771299, 2011). "If anything, insulin, a life-saving hormone, has improved dramatically the life expectancy of patients with diabetes." (PMID 21668983, 2011). "In both studies, the resulting islet-like cells were reported to display glucose-stimulated insulin secretion and, following in vivo transplantation, reversed streptozotocin-induced diabetes for extended periods of time." (PMID 21716654, 2011). "Insulin glargine is a synthetic long-acting insulin product used for patients with diabetes mellitus." (PMID 22187651, 2011). "The insulin-secreting function of pancreatic β-cells is one of the most critical aspects in the development of diabetes and insulin release from pancreatic β-cells plays an essential role in blood glucose homeostasis." (PMID 22216196, 2011). "Our results show that disruption of miRNA processing in mouse pancreatic β-cells, while compatible with β-cell development, leads to defective insulin-secreting function and progressive overt diabetes mellitus." (PMID 22216196, 2011). "Diabetes significantly reduced the total insulin content of isolated islets from the three groups of animals." (PMID 21912535, 2011). "Twenty four pubertal and adolescent diabetics with low BMD were recruited before starting any drug therapy other than insulin." (PMID 21961506, 2011). "All patients with diabetes have their glucose checked prior to elective surgery, and insulin therapy is started based on written protocols." (PMID 21912542, 2011). "A number of ways to improve insulin sensitivity have been proposed, because early treatment and prevention play a pivotal role in reducing the population burden of diabetes." (PMID 21439094, 2011). "The inability to produce insulin endogenously precipitates the clinical symptoms of type 1 diabetes mellitus." (PMID 22073210, 2011). "Related to the second aim hypoglycemic events, child age, diabetes duration, insulin regimen and comorbid diseases were included as covariates." (PMID 22185481, 2011). "Diabetes mellitus (DM) is a group of diseases characterized by high blood glucose levels that result from defects in the body's ability to produce and/or use insulin." (PMID 21851636, 2011). "Though different types of oral hypoglycemic agents are available along with insulin for the treatment of diabetes mellitus, healers heavily relied upon medicinal plants and herbs to treat diabetes." (PMID 21811514, 2011). "Another example is the use of fasting C-peptide as a substitute for insulin in determining HOMA-IR which can be applied to subjects with insulin-treated diabetes." (PMID 22112229, 2011). "Reduced insulin gene expression and concomitant reduced insulin secretion preceded the hyperglycaemic state and diabetes development." (PMID 22216196, 2011).
diabetes (continued). "CCDSS (Camit S1) analyzed and summarized blood glucose data for Insulin dosing in outpatients with diabetes." (PMID 21824384, 2011). "The cells extracted by this method are not only useful for studies of insulin expression specifically for diabetes gene therapy, but they also have potential to become a model for L-cell line physiology and activity studies in vitro." (PMID 22047106, 2011). "Although the majority of research in AD has focused on the amyloid beta (Aβ) peptide and how it is generated and metabolized, the role of insulin, glucose regulation and diabetes has been a constant area of research." (PMID 22654727, 2011). "More precisely, the pathophysiology section of the study had questions on the topic of pro-insulin, as well as on the effect of diabetes on the pancreatic hormones, beta cell mass and adiponectin." (PMID 21569337, 2011). "NO signalling, which is involved in the regulation of food intake and insulin signalling, is altered in obesity and diabetes." (PMID 21235803, 2011). "Type 1 (insulin-dependent) diabetes, induced by peripubertal autoimmune destruction of insulin-producing pancreatic β-cells, comprises approximately 10% of diabetes cases worldwide, with the rest attributed to Type 2 (non-insulin-dependent) diabetes." (PMID 21633715, 2011). "In patients an optimal treatment of diabetes involves control of glycemia by insulin administrations under haemoglobin A1c (HbA1c) monitoring." (PMID 21559266, 2011). "When rats are injected with streptozotocin during the neonatal period, it resembles human type 2 diabetes mellitus with respect to abnormalities in insulin secretory responses." (PMID 19584081, 2011). "Diabetes is a chronic metabolic condition characterized by elevated blood glucose levels related to insulin resistance and impaired insulin secretion." (PMID 22177279, 2011). "In young children with type 1 diabetes mellitus (T1DM) parents have full responsibility for the diabetes-management of their child (e.g. blood glucose monitoring, and administering insulin)." (PMID 21492413, 2011). "Insulin analogues are increasingly considered as an alternative to human insulin in the therapy of diabetes mellitus." (PMID 21736748, 2011). "Retinal transcriptomic and histological analysis also clearly demonstrated that local administration of insulin and systemic glycemia normalization use different pathways to counteract the effects of diabetes on the retina." (PMID 22046295, 2011). "Studies on EA treatment of diabetes in animal models have shown that EA leads to a reduction in plasma glucose levels by promoting insulin production and improves insulin sensitivity by inducing secretion of endogenous β-endorphin." (PMID 21799686, 2011). "Together, the findings of this study demonstrate the ability of chronic insulin therapy, initiated after one and a half months of uncontrolled diabetes, to normalize the majority of retinal gene expression changes." (PMID 21575160, 2011). "The metabolic derangements characteristic of diabetes in general is primarily a consequence of relative insufficiency of insulin secretion and/or insulin action." (PMID 22169757, 2011). "This is quite remarkable because, according to base line data, the duration time of diabetes in the insulin pretreated group was more than 10 years." (PMID 22196251, 2011). "Use of oral hypoglycemic agents and administration of insulin are cornerstones of treatment for diabetes mellitus." (PMID 21234246, 2011). "Diabetes mellitus (DM) is a group of metabolic diseases characterized by hyperglycemia resulting from defects in insulin secretion, insulin action, or both; the incidence of diabetes is increasing worldwide." (PMID 21603234, 2011). "Our pathway analysis of the effects of phloridzin and local insulin on the retinal transcriptome changes induced by diabetes clearly demonstrated that only local insulin specifically repressed retinal inflammation, particularly the complement activation." (PMID 22046295, 2011).